ATM (ATM serine/threonine kinase)
Diseases named in the same sentence as ATM in open-access papers (continued):
Sharing a sentence is not in itself a finding about the gene and the disease.
bladder cancer (continued). "Moreover, the ATM-MT group showed a higher mutation load and stronger antigen-specific immunity than the ATM-WT group in the immunotherapy cohort, TCGA-Bladder cancer cohort and GDSC-Bladder cancer cell line dataset (P < 0.05)." (PMID 32922441, 2020). "In early studies with prostate and bladder cancer cell lines, DAB2IP knockdown increased resistance to ionizing radiation but rendered them sensitive to combined treatment with genotoxic drugs such as the bacterial cytolethal distending toxin (CdtB) or an ATM inhibitor." (PMID 38902547, 2024).
chronic lymphocytic leukemia (53 papers, 2004 to 2025). "ATM germline variants have been shown to increase hematopoietic malignancy risk in adults, and the odds ratio for chronic lymphocytic leukemia is 14.8347." (PMID 40766138, 2025). "The protein kinase Ataxia-Telangiectasia Mutated (ATM) gene located on the 11q22.3 chromosome is frequently deleted in cases of chronic lymphocytic leukemia (CLL)." (PMID 38731871, 2024). "One trial aims to induce synthetic lethality in cells with ATM deficiencies, specifically chronic lymphocytic leukemias (CLL) that are ATM deficient (NCT01955668)." (PMID 33498525, 2021). "LOH events involving the ATM locus and ATM protein deficiency occur in 14% and 34%, respectively, of patients with chronic lymphocytic leukemia (CLL) and have been found to correlate with aggressive disease and worse outcome." (PMID 28356161, 2017). "Mutations in ataxia-telangiectasia mutated (ATM, the gene mutated in A-T) have also been detected in sporadic lymphoid tumors, such as T-cell prolymphocytic leukemia, B-cell chronic lymphocytic leukemia and mantle cell lymphoma." (PMID 21980358, 2011). "Also, the clinical efficacy of CC-115 was demonstrated in relapsed/refractory CLL/small lymphocytic lymphoma patients harboring ATM deletions/mutations." (PMID 34732266, 2021). "Furthermore, it was shown that olaparib induces significant killing of ATM-deficient lymphoid tumour cells from patients with chronic lymphocytic leukaemia." (PMID 29665859, 2018). "Interestingly, chronic lymphocytic leukemias with SF3B1 mutation were associated with a cryptic 3′ss activation of ATM exon 46, leading to ATM truncation." (PMID 26732650, 2016). "In chronic lymphocytic leukemia (CLL), somatic mutations in ATM have previously been reported in 7–16% of cases, while the ATM gene, located in the q-arm of chromosome 11, is recurrently deleted in 10–24% of patients." (PMID 40275070, 2025). "Despite the well-established adverse impact of del(11q) in chronic lymphocytic leukemia (CLL), the prognostic significance of somatic ATM mutations remains uncertain." (PMID 40275070, 2025). "Another study reported that inhibition of ATR is effective against cancer cells in ATM-defective chronic lymphocytic leukemia." (PMID 36765693, 2023). "In chronic lymphocytic leukemia, patients with 11q (ATM gene locus) deletion generally displayed a more aggressive clinical course and inferior prognosis in a younger subgroup." (PMID 36635772, 2023). "A-T patients with inactivating mutations in ATM sporadically have T cell prolymphocytic leukemia (T-PLL), B cell chronic lymphocytic leukemia (B-CLL), and mantle cell lymphoma (MCL)." (PMID 35432317, 2022). "In B-cell chronic lymphocytic leukemia, ATM was found to physically interact with TCL1A protein, and this association activates the NF-κB pathway in the regulation of apoptosis." (PMID 33859327, 2021). "Simvastatin has been reported to activate ATM when it is used to treat chronic lymphocytic leukemia patients." (PMID 30893303, 2019).
chronic lymphocytic leukemia (continued). "In this regard, it has been reported that in ATM-defective chronic lymphocytic leukemia cells, inhibition of ATR signaling by AZD6738 leads to an accumulation of unrepaired DNA damage that results in cell death by mitotic catastrophe." (PMID 28580318, 2017). "The 11q14·1‐q23·2del Chr11q/ATM deletions present in patient FR4 have been reported in 30% of chronic lymphocytic leukaemia cases and at a lower rate in ALL." (PMID 26205622, 2015). "The deletion of 11q (del(11q)) invariably comprises ATM gene in chronic lymphocytic leukemia (CLL)." (PMID 31974435, 2020). "Remarkably, CC-115, a dual inhibitor targeting DNA-PK and the structurally related mammalian target of rapamycin kinase (TORK), was shown to induce caspase-dependent cell death in primary chronic lymphocytic leukemia (CLL) cells and to be clinically effective in CLL patients with an ATM mutation." (PMID 31921645, 2019). "Moreover, somatic mutations spreading in the ATM gene have been identified in a range of cancer types, including mantle cell lymphoma (MCL), B-cell chronic lymphocytic leukemia (B-CLL), T cell prolymphocytic leukemia (T-PLL), breast, colorectal, lung, and prostate cancers." (PMID 34771661, 2021). "Similarly, we also observe co-mutations characteristic of chronic lymphocytic leukemia (CLL); 6 out of 16 (37.5%) cases of trisomy 12 co-occurred with a mutation in NOTCH1, MYD88, or FBXW7; 2 out of 9 (22%) deletions on chr13q co-occurred with a ATM mutation." (PMID 33436578, 2021). "PARP inhibitors, such as olaparib, are already in clinical use for treatment of solid tumors and in clinical trials for patients with chronic lymphocytic leukemia and T-PLL and could prove useful for treatment of many other malignancies driven by ATM deficiency." (PMID 26536348, 2015). "Recently, ATM-deficient mantle cell lymphoma, chronic lymphocytic leukemia, and T-prolymphocytic leukemia have been shown to be more sensitive to PARP inhibitors than ATM-proficient cells suggesting that ATM mutation/inactivation might predict responses of individual tumors to PARP inhibitors." (PMID 24252502, 2013). "ATM is also biallelically lost in nearly all T cell prolymphocytic leukemias (T-PLL), 50% of mantle cell lymphomas (MCL) and 5–10% of chronic lymphocytic leukemias (CLL)." (PMID 32015826, 2020). "Most of the ATM gene in patients with B-cell chronic lymphocytic leukemia (CLL) is defective." (PMID 33036137, 2020).
mantle cell lymphoma (52 papers, 2003 to 2025). Mantle cell lymphoma is a rare form of malignant non-Hodgkin lymphoma affecting B lymphocytes in the lymph nodes in a region called the ``mantle zone''. "ATM mutations are found in many solid tumors (breast, ovarian, colorectal, and prostate) and hematological malignancies; in addition, inactivating mutations of ATM characterize half of mantle cell lymphoma and T‐cell prolymphocytic leukemia patients." (PMID 39492835, 2024). "In myeloid malignancies, multiple alterations were noted in TET2 (n = 142, including 24/43 or 56% of AITL samples) and DNMT3A (n = 35), while in mantle cell lymphoma, ATM (n = 14, 10%) frequently harbored multiple mutations." (PMID 37898613, 2023). "ATM is also one of the commonly mutated genes in mantle cell lymphoma (MCL) and lung adenocarcinoma." (PMID 35586092, 2022). "This meets previous evidence in mantle cell lymphomas, gastric and colorectal tumors harboring mutations in ATM that result in loss or decrease of protein function and higher sensitivity to PARPis." (PMID 33888065, 2021). "Somatic mutations in ATM are present in several cancers including hematologic malignancies (e.g., are present in about 45% of mantle cell lymphoma cases), hepatocellular cancer, CRC, skin cancer, BC and others, however, only rarely mutated in OvC." (PMID 32605254, 2020). "A synthetic lethal siRNA screen applied on mantle cell lymphoma with deficient ATM showed an improvement in sensitivity to ATR inhibitors." (PMID 33036137, 2020). "Olaparib is a well-known PARP inhibitor that has been used in preclinical studies on patients with CLL, mantle cell lymphoma, and gastric cancer with ATM-deficient leukemic cells and demonstrated activity as a single-agent." (PMID 33036137, 2020). "Combining the 9 studies then as described in Methods, gave 70.26 [95% CI = 34.59–142.72] as the minimum odds ratio that a mantle cell lymphoma contains an ATM mutation." (PMID 17683622, 2007). "In addition, ATM has been associated with HRR, and ATM-deleted mantle cell lymphoma showed increased sensitivity to PARPi." (PMID 37020276, 2023). "For example, ATM is recurrently mutated in up to 50% of mantle cell lymphoma (MCL)." (PMID 33066395, 2020). "Furthermore, nearly 45% of mantle cell lymphoma cases had mutations which involved either truncated ATM protein or missense mutations disrupting the PI3K domain." (PMID 33036137, 2020). "For example, nearly 50 % of cases of mantle cell lymphoma contain mutations or deletions in ATM." (PMID 27613518, 2016). "For instance, ATM mutations are highly prevalent (approx. 50%) in mantle cell lymphoma patients, raising the possibility that these tumors might be selectively treated with a FA pathway inhibitor." (PMID 20043851, 2009). "For example, alterations in ATM have been implicated in mantle cell lymphoma (MCL), chronic lymphocytic leukemia (CLL), and myelodysplastic syndrome (MDS)." (PMID 34840720, 2021). "Consistently, another study reported that the depletion of Skp2 decreases phosphorylated ATM protein levels in cisplatin-resistant mantle cell lymphoma JeKo-1 cell line and the downstream-acting factors of ATM that directly participates in DNA repair." (PMID 34068643, 2021). "PARP inhibitors are extremely efficient against cancer cells bearing ATM defects, as shown in the context of mantle cell lymphoma." (PMID 27844328, 2017).
mantle cell lymphoma (continued). "Evidently, Skp2-deficiency is more effective in increasing cisplatin cytotoxicity in cisplatin-resistant cells than the inhibition of ATM, suggesting Skp2 is likely to be a more promising target than ATM in the treatment of cisplatin-resistant mantle cell lymphoma (MCL)." (PMID 34068643, 2021). "Cotreatment of mantle cell lymphoma (MCL) cells with AF and ABT-888 (PARPi) increases synergistically the apoptosis of ATM-proficient MCL cells, with increased γ-H2AX foci induction in the DNA and depletion of p-Chk1 (a downstream target of ATR signaling)." (PMID 29770165, 2018). "Germline mutations in this gene cause the Ataxia Telangectasia cancer susceptibility syndrome, and ATM deficiencies (mutations or lack of expression) are also frequent in sporadic hematological malignancies such as chronic lymphocytic leukemia and mantle cell lymphoma." (PMID 20043851, 2009). "Aberrations at the ATM locus have been observed in Chronic Lymphocytic Leukemia (CLL), T-cell prolymphocytic leukemia (T-PLL) diffuse large B-cell lymphoma (DLBCL), mantle cell lymphoma (MCL) and cutaneous T cell lymphoma (CTCL)." (PMID 38347838, 2024).
lung adenocarcinoma (51 papers, 2011 to 2025). A carcinoma that arises from the lung and is characterized by the presence of malignant glandular epithelial cells. "This has been previously performed in two cohorts of patients with lung adenocarcinoma, demonstrating a significant enrichment for germline pathogenic variants in ATM in cases compared to controls." (PMID 36865800, 2023). "ATM is one of the most common genes that is somatically mutated in cancer, in particular in lung adenocarcinomas." (PMID 35628590, 2022). "The ATM mutated patients with TUBA1C low expression showed better survival than patients with over-expression of TUBA1C in lung adenocarcinoma (LUAD) (P = 0.03, log-rank test)." (PMID 36180906, 2022). "Up to 40% of lung adenocarcinoma have been reported to lack ataxia-telangiectasia mutated (ATM) protein expression." (PMID 31481733, 2019). "Using publicly available databases, we show that both ATM mutation and ATM deficiency (diploid versus amplified) are associated with olaparib sensitivity in a panel of human lung adenocarcinoma cell lines." (PMID 31481733, 2019). "Analysis of drug sensitivity data from 61 lung adenocarcinoma cell lines in the GDSC database revealed that cell lines with ATM mutation were significantly more sensitive to olaparib than those with wild-type ATM." (PMID 31481733, 2019). "Our findings also report frequent frameshift mutations in the ATM tumor suppressor gene leading to protein truncation in patients with lung adenocarcinoma." (PMID 30093964, 2018). "ATM is also significantly mutated in lung adenocarcinomas, kidney clear cell carcinomas, and prostate adenocarcinomas." (PMID 29522538, 2018). "Loss-of-function mutations in the DNA damage response kinase ATM are common in lung adenocarcinoma but directly targeting these with drugs remains challenging." (PMID 27922010, 2016). "We therefore sought to determine the frequency of ATM loss in a tissue microarray (TMA) of lung adenocarcinoma." (PMID 27259260, 2016). "We addressed this in the present study by examining the role of the ataxia telangiectasia mutated (ATM) signaling pathway in response to LDR using A549 human lung adenocarcinoma cells and HBE135-E6E7 (HBE) normal lung epithelial cells." (PMID 27708248, 2016). "In this study, we observed that ATM rs189037 AA genotype carriers were more susceptible to lung adenocarcinoma than GA or GG genotype carriers in a recessive model." (PMID 24819391, 2014). "Overall association, stratification analysis and combined analysis between ATM rs189037 polymorphism and lung adenocarcinoma risk." (PMID 24819391, 2014). "This repair pathway can be disrupted by mutations in BRCA1, BRCA2, or ATM (ataxia telangiectasia mutated), found in 7% of lung adenocarcinomas." (PMID 25505733, 2014). "Meanwhile we explored the combined effects of cooking oil fumes exposure and ATM rs189037 polymorphism on lung adenocarcinoma risk." (PMID 24819391, 2014). "This study showed that the individuals with ATM rs189037 AA genotype were at an increased risk for lung adenocarcinoma compared with those carrying the GA or GG genotype (adjusted odds ratios (OR) 1.44, 95% confidence interval (CI) 1.02–2.02, P = 0.039)." (PMID 24819391, 2014). "The tumour sequencing project (TSP), a large-scale exon-directed sequencing experiment to classify recurring somatic mutations in lung adenocarcinoma, found that 7% of 188 lung adenocarcinoma patients analysed harboured mutations in ATM." (PMID 25247188, 2014).